NAT2 (N-acetyltransferase 2)
Diseases named in the same sentence as NAT2 in open-access papers (continued):
Sharing a sentence is not in itself a finding about the gene and the disease.
salivary gland tumors (1 paper, 2021). "We harvested the CRTC1-MAML2 fusion–induced salivary gland tumors (T1, T2) and their matched tumor-adjacent normal tissues (NAT1, NAT2), along with normal salivary gland tissues from the control nontransgene carrier littermates (N1, N2)." (PMID 33830080, 2021).
Tinnitus (1 paper, 2017). Tinnitus is an auditory perception that can be described as the experience of sound, in the ear or in the head, in the absence of external acoustic stimulation. "Potentially individuals carrying the allele A/T of GRM7 and slow acetylator phenotype of NAT2 (the later one with smaller statistic relevance) are prone to develop a more severe form of tinnitus, that requires specific therapeutic interventions and ideally personally tailored." (PMID 29163129, 2017). "The odds of developing severe tinnitus was relatively higher in the presence of slow acetylator phenotype of NAT2 when compared to intermediate acetylator." (PMID 29163129, 2017). "Logistic regression model in the NAT2 applied to severe tinnitus considering intermediate acetylator as reference." (PMID 29163129, 2017). "This is the first study evaluating the effect of GRM7 and NAT2 gene in tinnitus." (PMID 29163129, 2017). "Considering the Tinnitus Handicap Inventory scores, we found significant association between severity of tinnitus (grades severe and catastrophic from THI) and the presence of NAT2 gene (please see more details in the next sub-heading)." (PMID 29163129, 2017). "No other studies were found relating GRM7, NAT2 and tinnitus." (PMID 29163129, 2017).
tuberculous meningitis (1 paper, 2024). "This study examines the influence of varying isoniazid (INH) dosages and NAT2 gene polymorphisms on the clinical characteristics, therapeutic approaches, and prognostic outcomes of patients with tuberculous meningitis (TBM) within the specified region." (PMID 39902038, 2024).
Wilson disease (1 paper, 2024). A very rare inherited multisystemic disease presenting non-specific neurological, hepatic, psychiatric or osseo-muscular manifestations due to excessive copper deposition in the body. "Our study suggests that individuals with Wilson’s disease or ATP7B-defective alleles who also harbor NAT2 UAs may be at increased risk of INH-induced hepatotoxicity." (PMID 38424191, 2024).
cancer (61 papers, 1998 to 2025). A tumor composed of atypical neoplastic, often pleomorphic cells that invade other tissues. "Polymorphisms in NAT2 (another enzyme involved in metabolizing coffee components) have been linked to different cancer risks with coffee intake, though NAT2 is less crucial for CAF itself." (PMID 40650030, 2025). "In general, slow metabolizers have higher rates of certain types of cancer and are more susceptible to adverse effects from chemicals metabolized by NAT2." (PMID 38927494, 2024). "A high frequency of NAT1 and NAT2 polymorphisms makes humans prone to cancer when exposed to aromatic and heterocyclic carcinogens." (PMID 37174036, 2023). "Arylamine N-acetyltransferase 2 has been related to drug side effects and cancer susceptibility; its protein structure and acetylation capacity results from the polymorphism’s arrays on the NAT2 gene." (PMID 37023111, 2023). "Genetic polymorphisms in NAT1 or NAT2 are associated with increased cancer risk at numerous sites including urinary bladder and head and neck cancers." (PMID 35281898, 2022). "The role of NAT1 and NAT2 acetylator polymorphisms in cancer risk from aromatic and heterocyclic amine carcinogens will become clearer with more precise determinations of both exposures and genotypes." (PMID 24151610, 2013). "The study of mutations in GSTP1 and NAT2 genes is necessary in assessing the risk of the development of various diseases, such as cancer." (PMID 29805847, 2013). "NAT2 polymorphisms modify individual cancer risk and drug response, or susceptibility to adverse drug reactions." (PMID 23497148, 2013). "It was previously shown that patients with NAT2 slow acetylator genotypes (homozygous for NAT*5, NAT*6, and NAT2*7 alleles) are significantly (P < 0.002) more prone to develop UADT cancer (0.37) as compared with controls (0.22)." (PMID 24151610, 2013). "The high frequency of the NAT2 acetylation polymorphisms in human populations together with ubiquitous exposure to aromatic and heterocyclic amines suggest that NAT2 acetylator genotypes are important modifier of human cancer susceptibility." (PMID 22403658, 2012). "For instance, for cancers in which N-acetylation is a detoxification step such as aromatic amine-related urinary bladder, NAT2 slow acetylator phenotype seems at higher risk." (PMID 16827944, 2006). "The NAT2 slow acetylator phenotype is associated with cancer risk and adverse drug reactions." (PMID 38001469, 2023). "Generally, NAT2 genetic variants have been linked to decreased enzymatic activity and variable stability, leading to an imbalance in the xenobiotic detoxification and increased susceptibility to different forms of cancer." (PMID 33706752, 2021). "The acetylation rate has a great influence by the NAT2 gene due to the presence of various SNPs, and it may affect the drug metabolism and susceptibility to some diseases such as cancer." (PMID 32626768, 2020). "The NAT2 gene is highly polymorphic with more than a hundred described variant alleles, and alterations in its structure lead to a variety of responses such as susceptibility of cancer and adverse drug reactions." (PMID 33369472, 2020). "The NAT2 acetylated genotype has a large influence on cancer predisposition and may induce susceptibility to tumors arising from industrial and environmental aryl amines." (PMID 33369472, 2020). "Therefore, the acetylation capacity in humans has been linked to NAT2 polymorphisms, which alters susceptibility to cancer and other diseases including adverse drug reactions." (PMID 29371971, 2017). "The NAT1 and NAT2 polymorphic variants may influence the metabolism of arylamine carcinogens and modulate the individual susceptibility to cancer upon exposure to environmental risk factors." (PMID 25886288, 2015). "Genetic variation of NAT2 may lead to differences in the rate of arylamine metabolism and consequently increase cancer risk." (PMID 24586291, 2014).
cancer (continued). "Gene-gene interaction testing has shown several cancer-NAT2 associations." (PMID 24151610, 2013). "Moreover, the association with NAT1*11/NAT2*6A haplotypes was correlated to the risk of UADT cancer (OR = 1.54; P = 0.03)." (PMID 24151610, 2013). "NAT2*5 and NAT2*6 alleles seem to be associated with cancer risk." (PMID 24151610, 2013). "Previous studies have implicated NAT2 polymorphisms as risk factors for various types of cancer." (PMID 23226745, 2012). "Alterations to the NAT2 acetylator status caused by variations in the NAT2 gene have been reported to reduce enzymatic activity, resulting in inefficient detoxification and thus leading to increased cancer susceptibility." (PMID 23226745, 2012). "Polymorphisms of NAT2 may lead to differences in the rate of arylamine metabolism and consequently cancer risk." (PMID 23226745, 2012). "The aims of this study are to refine the phenotype inference of NAT2 genotyping and the identification of clinically relevant associations of the new genotype categories with cancer risk, differential treatment response or clinical outcome are beyond the aims of the study." (PMID 22970273, 2012). "Possible correlations of NAT2 polymorphisms with cancer risk were evaluated by the meta-analyses." (PMID 23226745, 2012). "We hypothesized that NAT1 and/or NAT2 polymorphisms contribute to the increased cancer evident in IBD." (PMID 17537267, 2007). "As certain NAT2 genotypes may render susceptibility to cancer risk, perhaps a collaborative effort where specific NAT2 genotypes are investigated with uniform study design, analysis, reporting and exposure variables in different ethnic groups is needed." (PMID 16827944, 2006). "The alteration of NAT2 acetylator status caused by polymorphosms in NAT2 gene may induce the decrease of enzyme activity and the absence of efficiency in detoxification, thus contributing to increasing cancer susceptibility." (PMID 28915684, 2017). "NAT2 may have conflicting associating results for cancer risk in the same population." (PMID 18423013, 2008). "Polymorphism in other genes, such as N-acetyl metastases 2 (NAT2) and glutathione S-metastases (GSTM1) is also related to the increased cancer risk of RCC in the smokers." (PMID 38957811, 2024). "Specifically NAT2 is a target in nine different clinical trials against diverse cancers, significantly highlighting its essential role in driving hallmark processes in unrelated cancers." (PMID 39484215, 2024). "NAT2 and GSTM1 play a role in the breakdown and elimination of cancer-causing substances present in tobacco, thus forming the basis of this connection." (PMID 38957811, 2024). "Individuals with a slow NAT2 acetyl genome and GSTM1-NULL genotype exhibit impaired metabolic ability, leading to an increased risk of these cancers." (PMID 38957811, 2024). "The N-Acetyltransferase 2 (NAT2) gene encodes a key enzyme involved in xenobiotic metabolism, which contributes to the detoxification of numerous cancer therapy-induced products." (PMID 33369472, 2020). "Taken together, these results suggest that NAT2-targeted therapy can be beneficial to a larger number of cancer patients." (PMID 33384440, 2020). "However, the NAT2-allele selective therapy may have broader cancer applicability." (PMID 33384440, 2020). "Taken together, these results demonstrate SMRT sequencing as a valid haplotyping tool to predict NAT2 acetylator phenotypes in cancer patients and their tumors." (PMID 33384440, 2020). "In humans, besides their influence on the effectiveness of prescribed medications, polymorphisms at NAT2, and also at NAT1, have been associated with differential susceptibility to various cancers linked to arylamine exposure." (PMID 31068377, 2019). "Amongst the 3 upregulated genes, CYP2C19 and NAT2 have long been reported to participate in the failure of anticancer agents treatment or the increased occurrence of cancers." (PMID 31551763, 2019).
cancer (continued). "A second set consisted of an additional 15 cancer-related genes (Nf1, Mki67, Mllt4, Fgfr2, Ctnnb1, Fat1, Clp1, Fat4, Arid1a, Nat1, Nat2, Setd2, Impg1, Nbas and Npat)." (PMID 29925311, 2018). "Genetic mutations, such as NAT2 slow acetylation and GSTM null genotypes, have previously been shown to be associated with increased susceptibility to cancer." (PMID 27000312, 2016). "Increased cancer risk has been associated with functional polymorphisms that occur within the genes coding for the N-acetyltransferase enzymes NAT1 and NAT2." (PMID 9528834, 1998). "Our study revealed the high prevalence of slow acetylators of NAT2 (60.42%) in the studied samples among Al-Ahsa population which might alter drug's efficacy and vulnerability to some diseases, like cancer." (PMID 32626768, 2020). "Most of the association studies of NAT2 in Arab countries were focusing on cancer susceptibility rather than its interaction with isoniazid, the antituberculosis drug." (PMID 33277594, 2020). "As an essential phase II enzyme, NAT2 is key in the process of cancer development." (PMID 28915684, 2017). "The frequencies of NAT1 and NAT2 genotype varies according to racial and ethnic background, and the frequency difference may be a factor in cancer incidence." (PMID 29165164, 2017). "NAT2 polymorphisms did not significantly modulate the cancer risk after interaction with environmental factors, such as tobacco, alcohol or occupational exposure." (PMID 24586291, 2014). "The distribution of genotypes of NAT2 in control and cancer patients is shown in." (PMID 16083506, 2005). "However, they may also share changes in some genes (like GSTM1 and NAT2) that make it hard for their bodies to break down certain toxins, which can make them more likely to get cancer." (PMID 41018918, 2025). "NAT2 is polymorphic, and it was thought that NAT2 acetylation status alteration caused by NAT polymorphisms decreased enzymatic activity and result in absence of detoxification efficiency, which could lead to an increase in cancer susceptibility." (PMID 24586291, 2014). "Finally, we did not obtain detailed information on cancer metastasis and survival, which restricted further analyses of the roles of the NAT2 polymorphisms in ESCC progression and prognosis." (PMID 24586291, 2014). "Thus, NAT2 might carry a protective role against cancer development." (PMID 37478088, 2023). "The linkage disequilibrium between the genes of NAT1 and NAT2 has been observed in HNC and other cancers." (PMID 34684132, 2021). "Although most studies have focused on the role of NAT1 and NAT2 genetic polymorphisms in COAD risk, the potential role played by their aberrant expression in COAD has largely been ignored and whether NAT1 and NAT2 expression influences cancer patient survival remains unknown." (PMID 34322151, 2021). "We reasoned that anti-cancer drugs rendered less toxic by NAT2 metabolism are also likely to exist and that CRC cells having lost a rapid NAT2 allele through LOH could be sensitized to treatment with a cytotoxic NAT2 substrate relative to other constitutional cells retaining the rapid allele." (PMID 32161261, 2020). "Additionally, both the proximal and the distal gene to the SNP, NAT2 and PSD3, respectively, are strongly correlated with both cancer and T2D." (PMID 35884374, 2022). "Data reported by the Cancer Cell Line Encyclopedia (CCLE) indicates the MDA-MB-231 cell line is diploid for NAT2 and does not show copy number variation." (PMID 35046826, 2021). "While the NAT2 isoenzyme has a major role in the metabolism of xenobiotics, including therapeutic drugs and carcinogens, growing evidence supports an additional role for NAT1 in physiological processes (notably folate and methionine metabolism) and cancer cell biology." (PMID 31068377, 2019).
tumor (17 papers, 2005 to 2024). "First, we construct CRC cell model systems to assess the applicability of APA treatment in cases where the tumor is left with the slow NAT2 alleles belonging to the groups NAT2*5, NAT2*7 and NAT2*14." (PMID 33384440, 2020). "Once these variants are identified, accurate haplotype resolution at the NAT2 locus of normal and tumor samples is required for diagnostic purposes." (PMID 33384440, 2020). "Tumor cells encoding the slow acetylator variants NAT2*5 and *14 indeed responded to APA treatment and had similar kinetic profiles when compared to cells expressing the *6 allele group." (PMID 33384440, 2020). "By calling 14 SNP positions in the NAT2 locus, we were able to define tumor and normal haplotypes in each patient and identify allele losses occurring in the former." (PMID 33384440, 2020). "For patients heterozygous for NAT2, we observed an almost equal probability of losing either allele after the tumor undergoes LOH." (PMID 33384440, 2020). "To better estimate the total number of treatable CRC patients, we here determined whether tumor cells retaining also other NAT2 low activity variants after LOH respond to APA treatment." (PMID 33384440, 2020). "NAT2 is one of the phase II enzyme that participate in the bioconversion of heterocyclic arylamines into electrophilic nitrenium ions, which are important ultimate carcinogens that are directly implicated in tumor initiation process." (PMID 16083506, 2005). "N-acetyltransferase 2 is phase II metabolizing enzyme that participates in the bioconversion of heterocyclic arylamines into electrophilic nitrenium ions, which are important ultimate carcinogens that are directly implicated in tumor initiation process." (PMID 16083506, 2005). "Thus, dapsone and xanthohumol may alter the tumor progression of high risk COAD patients by acting on NAT2 and LCAT, respectively." (PMID 36353119, 2022). "Due to chromosome arm LOH at 8p22 during the early development of CRC, a patient heterozygous for a rapid and a slow NAT2 allele may lose the rapid variant in the tumor cells, effectively rendering them deficient in NAT2 activity and sensitive to a cytotoxic substrate of NAT211." (PMID 33384440, 2020). "Later, NAT1 and NAT2 polymorphisms were associated with an increased risk of LSCC, and a correlation between NAT1*10/*11 genotype frequency and tumor location was also observed." (PMID 35406495, 2022). "The Wilcoxon rank-sum test revealed that the expression of NAT2 in tumor samples was significantly lower than that in normal samples." (PMID 34867333, 2021). "The chi-square test indicated that NAT2 expression was negatively related to tumor differentiation and AJCC stage in CRC (p = 0.03 and p = 0.02, respectively), which was confirmed by GSE17538 expression profiling." (PMID 34867333, 2021). "For diagnostic purposes, we finally develop a low-cost long-read sequencing protocol for the multiplexed NAT2 haplotyping of patient-matched normal and tumor samples." (PMID 33384440, 2020). "We detected LOH of NAT2 in 19 tumor samples (25.7%) of which 13 were from individuals with an intermediate acetylator phenotype." (PMID 33384440, 2020). "To evaluate APA’s anti-tumor activity in vivo, we xenografted athymic mice on each flank with rapid and slow NAT2 tumors and delivered a liposomal formulation of APA systemically." (PMID 32944621, 2020). "Next, we evaluated the response of patient-derived primary tumor samples to APA treatment and found that tumors homozygous for slow NAT2 acetylator alleles were, in general, more sensitive than those bearing a rapid acetylator allele." (PMID 32944621, 2020). "However, conventional Sanger sequencing as well as short read sequencing methods are not able to discern whether polymorphisms are present in the same allele or in different alleles of the NAT2 gene, thereby impairing the understanding of which specific allele has been lost in tumor cells." (PMID 33384440, 2020).